RNU6-1160P (RNA, U6 small nuclear 1160, pseudogene)
Gene: Small nuclear RNA gene on chromosome 9 (96,256,216 to 96,256,319, reverse strand). Ensembl gene ENSG00000207276.
Homologues: Orthologues: chimpanzee U6 (99% identical), guinea pig U6 (74% identical), rabbit U6 (66% identical), mouse Gm24737 (64% identical). Paralogues in human: RNU6-1251P (85% identical), RNU6-144P (85% identical), RNU6-16P (85% identical), RNU6-235P (85% identical), RNU6-39P (85% identical), RNU6-890P (85% identical), RNU6-1 (84% identical), RNU6-15P (84% identical), RNU6-2 (84% identical), RNU6-21P (84% identical), RNU6-33P (84% identical), RNU6-3P (84% identical), and 1285 more.